NF2 (NF2, moesin-ezrin-radixin like (MERLIN) tumor suppressor)
Diseases named in the same sentence as NF2 in open-access papers (continued):
Sharing a sentence is not in itself a finding about the gene and the disease.
cancer (continued). "Interestingly, the Enriched Drug Families table of this query highlighted Statins (p-value < 0.01) and Imatinib analogues (p-value < 0.01) as the only two classes of drugs significantly associated to drug sensitivity in cancer cell lines harbouring NF2 mutations." (PMID 26513174, 2015). "We previously demonstrated that cancer cells with low NF2 display increased sensitivity to pyrimidine analogs, including cytarabine and 5-fluorouracil." (PMID 40707702, 2025). "Future studies in these cancer fields must be conducted to fill this gap in the discernment of NF2 mutants’ effect on tumorigenesis as it relates to biological pathways like the Hippo signaling pathway." (PMID 39796693, 2024). "This review aims to update our understanding of the Neurofibromatosis 2 (NF2) gene and its role in the pathogenesis of various cancers." (PMID 39796693, 2024). "NF2 functions as a sensor in the cell-to-cell contact inhibition of the Hippo signaling pathway, and its levels increase as cancer cell density rises." (PMID 39431199, 2024). "We also evaluated GSTT1 polymorphism in our cohort as a gene mapping to cytogenetic band 22q11.23 which is near NF2 (22q12.2) that is also frequently deleted in various cancers." (PMID 39726707, 2024). "In this review, we sought to elucidate NF2’s role in cancer formation and provide insights into the cellular pathways involved in NF2 mutant-driven carcinogenesis." (PMID 39796693, 2024). "Conversely, inhibiting Hippo pathway effectors such as NF2/merlin, large tumor suppressor kinases 1 (LATS1), and 2 (LATS2) reinstates cancer cell susceptibility to ferroptosis, particularly at high cell densities." (PMID 39737174, 2024). "E‐cadherin activates NF2 to inhibit YAP activity in mesenchymal cancer cells, thereby preventing ferroptosis, a form of regulated cell death." (PMID 38700015, 2024). "Studies on NF2 involvement in these carcinomas are not extensive, and there remains much work to be done to understand how NF2 is involved in the carcinogenesis of these cancers." (PMID 39796693, 2024). "Another study showed that intercellular interactions determine iron death in cancer cells through NF2-YAP signaling." (PMID 37061535, 2023). "The combined inhibition of Bcl-xL and YAP synergistically suppressed cancer stemness and in vivo metastasis in RASA1 and NF2 co-deficiency." (PMID 37730636, 2023). "NF2 and RASA1 deficiency increased in vivo metastasis and in vitro tumorsphere formation by synergistically amplifying Wnt and YAP signaling in cancer stem cells (CSCs)." (PMID 37730636, 2023). "Venetoclax, a Bcl-2 inhibitor, reduced the increased tumorsphere size more efficiently in Nf2-KO S1 and NF2-KO SNU-668 cells than in control cells, indicating that Bcl-2 mediates the increased cancer stemness induced by NF2 deficiency." (PMID 37730636, 2023). "This revealed peaks for TEAD1 and TEAD4 on both KISS1 and CXCL8 promotors, suggesting that within cancer cells, TEAD transcription factors facilitate the expression of genes both up‐ and down‐regulated on NF2 loss." (PMID 36740402, 2023). "Genes in the E-cadherin-NF2-hippo-YAP pathway typically have malignant mutations that encourage metastasis, prevent cancer cells from dying, and boost their resistance to conventional cancer treatments." (PMID 37598126, 2023). "Gene enrichment analysis revealed DEGs involved in “MAPK signaling pathway” and “tight junction”, but no clear subgroup-specific dominant equivalent pathway as “pathways in cancer” in NF2 tumors." (PMID 36937440, 2023). "We assessed the antigrowth activity of GNE-7883 across 196 NF2 wild-type cancer cell lines spanning various indications." (PMID 37277530, 2023). "Traditionally, gene fusions in cancer are associated with activation, but fusions involving genes such as APC and NF2 have been shown to result in loss of protein function in the same way that a nonsense or frameshift DNA sequence variant would." (PMID 37646774, 2023).
cancer (continued). "We also found recurrent CRISPR-induced indels from both NRASG12V and KRASG12D screens in genes whose loss has been linked to ICC but that have not previously been shown to genetically interact with mutant RAS in this cancer including Brca2, Nf2, and Plk2." (PMID 35074757, 2022). "The phenotypes of these Nf2-mutant tumors are highly sarcomatoid, the cancer cells have a more spindle-like morphology and are dispersed throughout the liver." (PMID 35074757, 2022). "These class 2 (‘two-hit loss’) drivers include the genes RB1 (3/13 cancer types), NF1 (5/8), NF2 (1/2), PTEN (7/15), and BAP1 (2/6)." (PMID 34862370, 2021). "Meanwhile, NF2/YAP is an essential molecular signal that regulates ferroptosis and is also a gene responsible for malignant mutations found in cancer." (PMID 34123855, 2021). "Our analysis revealed that cancer cells with decreased NF2 expression display high sensitivity to DNA synthesis inhibition (Cytarabine, Oxaliplatin, and 5-Fluorouracil) and epidermal growth factor receptor (EGFR) targeted therapies (Gefitinib and Lapatinib)." (PMID 33805359, 2021). "The results showed that ATM, CHD4, FAT1, KMT2D, MED12, NF2, and SUFU were the most frequently mutated cancer-related genes." (PMID 33193598, 2020). "Conversely, SOX2 maintains cancer stem cells in osteoblastoma by direct inhibition of NF2 and WWC1, upstream activators of the Hippo pathway, leading to activation of YAP." (PMID 31100975, 2019). "Our analysis identified genomic alterations in members of the canonical Hippo pathway, including LATS1 and NF2 in some cancers, whose potential role in YAP activation warrants further investigation in each individual cancer type." (PMID 29985391, 2018). "We hope that our data serves as a starting point to further examine cancer vulnerabilities, in particular in FBXW7‐, RB1‐, or NF2‐mutated tumors." (PMID 29689640, 2018). "For instance, neurofibromin 2 (NF2, also known as Merlin), which is known to be mutationally inactivated in some cancers, is rarely mutated in FBC and initial genetic characterization of MBC did not unveil any alteration in core Hippo pathway components." (PMID 27248471, 2016). "These included several cancer-associated genes such as MKL1, EP300, NF2, and HIC2 and chromatin binding genes BRD1, HIRA, and HDAC10." (PMID 25909290, 2015). "AR42, similar to other HDAC inhibitors also decreased Akt phosphorylation, a pathway upregulated in many cancers and NF2." (PMID 24259290, 2013).
cancer (continued). "Merlin (NF2/schwannoma), is a tumor suppressor protein and boots innate immunity against cancer." (PMID 40104511, 2025). "This is particularly relevant because most current clinical trials focus on cancers with known mutations in Hippo pathway components, such as NF2; however, TEAD inhibitors may also suppress tumors independently of NF2 status." (PMID 41347094, 2025). "Some of the studies reviewed outline specific NF2 mutations which are commonly associated with a particular cancer type but do not detail how these different mutations relate to cancer formation." (PMID 39796693, 2024). "Imbalanced TEADs transcriptional output leads to the signal enhancement of many oncogenes, including KRAS, BRAF, LKB1, NF2, and MYC, and subsequently facilitates tumor progression, metastasis, cancer metabolism, and immunity, and serving as the hallmark of cancer." (PMID 38607003, 2024). "A cancer with a high frequency of mutational YAP/TAZ-TEAD activation is malignant pleural mesothelioma, an asbestos-induced lung tumor where forty percent of patients have deletions or loss-of-function mutations in LATS1, NF2, RASSF1, or SAV170." (PMID 38538573, 2024). "In other cancers, NF2 may play a less critical role and have an additive effect on the disease’s development." (PMID 39796693, 2024). "The cancer gene panel testing identified several genetic alterations, including a NF2 mutation, but no molecular target drug was found, and the patient died 6 months after surgery." (PMID 38739347, 2024). "Increased nuclear YAP1 levels have been found in solid tumors, and various Hippo pathway constituents have been altered in human cancer at the DNA level, including YAP1 and TAZ gene amplification, deletions, or truncating mutations in NF2, LATS1, and LATS2 gene." (PMID 39431199, 2024). "Several of the cancers reviewed in the present study had non-driver mutations in NF2 that contributed to promoting tumorigenesis but were not essential mutations of these cancers." (PMID 39796693, 2024). "NF2 acts as a driver mutation in some cancers, as a non-driver mutation in some cancers, and has simple associated mutations with other cancers." (PMID 39796693, 2024). "Not all the cancers studied had NF2 mutation implications to the same degree, with NF2 being a driver of mutation in some cancers, a non-driver of mutation in other cancers, and simply associated with mutations in other cancers." (PMID 39796693, 2024). "Notably, alterations of these proteins, such as NF2, E-cadherin, AMOT, and FAT1, are often observed in cancer and are associated with elevated YAP/TAZ activity." (PMID 38067201, 2023). "This further strengthens our hypothesis that NF2 and RASA1 deficiency induces changes in cancer stemness, as CSCs are capable of mimicking and modifying normal developmental processes to support cancer cell survival and proliferation." (PMID 37730636, 2023). "NF2 links signals from the cell membrane to growth-related gene expression and acts in cell–cell contact inhibition, a function defined as one of the hallmarks of cancer." (PMID 37280085, 2023). "Kyoto Encyclopedia of Genes and Genomes (KEGG) pathway enrichment analysis of differentially expressed genes with > threefold changes in Rasa1- and Nf2- KO tumorspheres compared to that in controls revealed the most pronounced changes in Pathways in cancer (KEGG 05200)." (PMID 37730636, 2023). "Thus, the inactivation of merlin (NF2)-Hippo pathway status has been proposed as a predictor of the sensitiveness of cancer cells to ferroptosis-induction therapies." (PMID 37180489, 2023).
cancer (continued). "Many studies have suggested that ferroptosis could be atherapeutic target for cancer, through the modulation of targets such as NF2(also known as merlin) -YAP signaling, the p62-Keap1-NRF2 pathway, theRas/Raf/MEK pathway, and ferritinophagy." (PMID 39077594, 2022). "However, we clearly demonstrate the presence of subclonal NF2 mutations in three patients, characterized by clonal mutation in other key MPM mutated cancer genes including BAP1, SETD2, and the TERT promoter." (PMID 34261524, 2021). "Furthermore, CAFs (CAF1, CAF2) showed higher expression of specific markers including a-SMA, fibronectin, and P4HA1, compared with NFs (NF1, NF2) and cancer cells (DLD-1, HCT-116), indicating the successful establishment of CAFs." (PMID 34930899, 2021). "Moreover, the diagnosis of spinal tumors, especially in children, can be an indicator of a cancer predisposition syndrome such as NF1, NF2, and VHL syndrome." (PMID 34574050, 2021). "NF2 has been illustrated to be downregulated in several types of human cancer." (PMID 32337368, 2020). "The stem cell transcription factor Sox2, a supposed marker for cancer stem cells and highly expressed in osteosarcoma, downregulates the Hippo activators merlin (Nf2) and WW domain-containing protein 1 (WWC1) and upregulates the Hippo suppressor Yes-associated protein 1 (YAP)." (PMID 32961800, 2020). "MPM exhibits a distinct genomic signature, including inactivating mutations in cyclin-dependent kinase inhibitor 2A (CDKN2A), and more recently, ubiquitin carboxyl-terminal hydrolase (BAP1) and neurofibromin 2 (NF2), have been shown to be the most prevalent in this type of cancer." (PMID 29342862, 2018). "Moreover, unlike the search for highly cytotoxic compounds aimed at killing aggressive, malignant tumors, NF2 patients require drugs that are well tolerated for long intervals of treatment and inhibit mutant but not normal cells." (PMID 29897904, 2018). "Besides the well-known MPM-associated genes, CDKN2A, NF2 and BAP1, other interesting cancer-associated genes were listed as frequently involved in a copy number loss (e.g. EP300, SETD2 and PBRM1)." (PMID 29371938, 2017). "In contrast to the TCGA-data, the ‘top 20’ list of ‘Cancer census genes’ most frequently involved in a copy number loss in the LP-WGS-data did not contain NF2, CDKN2A or BAP1." (PMID 29371938, 2017). "Combination Q in nano form with regular chemotherapeutic drugs like ADR and MTX in NF1 and NF2 respectively may overcome MDR—a daunting task in cancer treatment." (PMID 27196562, 2016). "Currently, a few clinical trials of anti-cancer drugs are underway for NF2." (PMID 24259290, 2013). "Thus far, these are undergoing clinical trials for mesothelioma and other NF2 mutant cancers (e.g., NCT04665206 and NCT04857372), although success against these cancers could spur future studies against various other YAPon cancers." (PMID 40440076, 2025).
cancer (continued). "However, inactivation or mutation of the neurofibrin 2 gene (NF2) has not attracted attention in cancer, because they are not common in common human malignancies." (PMID 32337368, 2020). "We next asked whether the cancer cell density‐YAP1‐LINC00152 axis is dependent on NF2 expression." (PMID 32042551, 2020). "No much is known about the NF2 (K20*) mutation in cancer patients." (PMID 29731991, 2018). "As observed in other cancer types, it is possible that non-mutational mechanisms may contribute to NF2 loss of function in a proportion of anaplastic meningiomas." (PMID 30202034, 2018). "Alternative splicing was pervasive, with recurrent high-magnitude events at cancer-relevant loci including GJA1 (SE), NF2 (A3/A5), LIN37 (A5), ECT2 (A3/A5), BCL2L11 (A3), UQCRH (A5), CSE1L (A3), BROX (A3), and multiple ZNFs." (PMID 41952686, 2026). "For cell cycle regulation and cancer, the genes CCND1 and E2F7 (cell cycle regulation) and BRCA2, NF2, BRCA1, and NF1 (cancer) were found to be upregulated relative to humans." (PMID 40149424, 2025). "Members of the MARK subfamily, including MARK2, 3 and 4, regulate the Hippo kinase cassette in diverse models including Drosophila, mice and human cancer cell lines by phosphorylating MST1/2, SAV and, as found in a recent study, NF2 and YAP/TAZ." (PMID 40869130, 2025). "Antagonizing the effects of forced YAP expression in YAPoff cancer contrasts the role of MORC2 in hepatocarcinoma, a YAPon cancer, in which it represses NF2 and KIBRA to promote YAP activity." (PMID 39172021, 2024). "Copy number deletions of cancer suppressor genes (including CDKN2A/B, FOCAD, NF2, etc.)are always accompanied by adjacent functional genes (including MTAP, MLLT3, etc.)deletion that synergistically contributes to oncogenesis." (PMID 37033966, 2023). "More recently, NF2 was found to be an upstream factor of nucleic acid sensing, suppressing cGAS-STING–initiated antitumor immunity in cancer cell models." (PMID 37280085, 2023). "The most abundantly studied are MAPK pathway inhibitors, and the common mechanisms of resistance are the reactivation of MAPK pathways such as DUSP7, NF2, and the KEAP1/Nrf2 pathway, which are present in multiple cancer resistance models." (PMID 38084101, 2023). "The data show that even in these highly CVM-1125-sensitive cancer cell lines, silencing of STK11 or NF2 was able to induce further reduction in cell viability compared with scramble control." (PMID 37351538, 2023). "CXCL12, the ligand of CXCR4, which is secreted from activated fibroblasts, was proven to stimulate cancer cell migration and promote cancer cell invasion through EMT transition, and is also elevated in CAF1 compared to NF1/NF2." (PMID 35853880, 2022). "In xenograft models of athymic nude mice subcutaneously injected with shNT-GPX4-iKO cells and shNF2-GPX4-iKO cells, knockdown of NF2 upregulates TFRC, ACSL4 and nuclear YAP, and doxycycline-induced GPX4 knockdown is able to eliminate cancer lesions." (PMID 35847022, 2022). "In contrast, H413 with HC and a strong cancer signature showed a reduction of cell junctional genes except for CTNNA1 and NF2." (PMID 35000271, 2022).